RN7SL286P (RNA, 7SL, cytoplasmic 286, pseudogene)
Gene: Miscellaneous RNA gene on chromosome 15 (32,602,121 to 32,602,411, forward strand). Ensembl gene ENSG00000277464.
Homologues: Orthologues: pig Metazoa_SRP (52% identical). Paralogues in human: RN7SL196P (100% identical), RN7SL539P (100% identical), RN7SL796P (99% identical), Metazoa_SRP (88% identical), RN7SL106P (88% identical), RN7SL238P (88% identical), RN7SL545P (88% identical), RN7SL759P (88% identical), RN7SL536P (88% identical), RN7SL185P (80% identical), RN7SL628P (80% identical), RN7SL82P (80% identical), and 701 more.